TCF7L2 (transcription factor 7 like 2)
Diseases named in the same sentence as TCF7L2 in open-access papers (continued):
Sharing a sentence is not in itself a finding about the gene and the disease.
schizophrenia (continued). "These preliminary results independently support previous findings regarding a possible role of TCF7L2 in susceptibility to schizophrenia, and strengthen the importance of integrating linkage analysis models of inheritance while performing association analyses in regions of interest." (PMID 22247771, 2012). "Therefore, evidence is emerging to support involvement of several independent SNPs within or flanking TCF7L2 in schizophrenia susceptibility; some of them may be population specific." (PMID 22247771, 2012). "Moreover, some variants of Tcf7l2 have been recently shown to be a risk factor in schizophrenia, and a group of synaptic genes involved in excitability has been found to be associated with the risk of schizophrenia." (PMID 23157480, 2012). "In support of shared genetic burdens, TCF7L2, the strongest genetic determinant for T2D risk in the human population, has been recently implicated in schizophrenia (SCZ) risk, suggesting that this may be one of many loci that pleiotropically influence both diseases." (PMID 22046400, 2011). "In addition, previous genome-wide analysis revealed that rare TCF7L2 mutations are associated with developmental disorders, like autism spectrum disorders (ASDs), and that TCF7L2 common intronic polymorphisms are associated with neuropsychiatric disorders, like schizophrenia and bipolar disorder." (PMID 36782064, 2023). "Reassuringly, many recapitulated genes are well-established for the traits, such as CACNA1C for schizophrenia, TCF7L2 for T2D, APOB for lipids, and STAT4 for autoimmune diseases." (PMID 33990562, 2021). "Intriguingly, a study of African-American patients with schizophrenia reported an interaction between APPs treatment and TCF7L2 under a multiplicative scale." (PMID 29713286, 2018). "While genes such as TCF7L2, TNF, APOE and BDNF-related genes can heighten T2DM and schizophrenia risk, other genes may have opposing impacts and lead to inconsistent and biased LDSR findings." (PMID 37477360, 2023). "In this study, the most strongly associated variant resides within an intron of the Parkin coregulated (PACRG) gene in schizophrenia patients with T2DM vs controls, and another variant that reached genome-wide significance resides within the intron of the TCF7L2 gene." (PMID 33315097, 2021). "Due to the current knowledge of biological role of this gene, HABP2 seems to us as less attractive potential schizophrenia susceptibility gene, compared to TCF7L2, although this may not necessarily be true." (PMID 22247771, 2012). "It has been demonstrated that a number of Wnt pathway elements, including GSK-3β, β-catenin, APC, TCF7L2, and FZD3, are connected to schizophrenia as well." (PMID 37780577, 2023). "Therefore, TCF7L2 may contribute to the comorbidity between schizophrenia and T2DM." (PMID 33315097, 2021). "Other candidate genes, such as insulin like growth factor 2 mRNA binding protein 2 (IGF2BP2) or transcription factor 7 like 2 (TCF7L2), may also contribute to the genetic basis of the co-occurrence of schizophrenia and T2DM." (PMID 33315097, 2021). "At the molecular biology level, the implication of a TCF7L2 effect on schizophrenia under the dominant model, is not clear and should be further investigated." (PMID 22247771, 2012).
dyslipidemia (24 papers, 2006 to 2025). "A recent study showed that dietary polyunsaturated fats (PUFA) modulated the genetic effect of TCF7L2 rs7903146 polymorphism on postprandial dyslipidemia." (PMID 40568560, 2025). "Our findings indicate that TCF7L2 polymorphisms are associated with dyslipidemia and altered lipid profile in the Balinese." (PMID 35341056, 2022). "One of the potential genetic risk factors for dyslipidemia is transcription factor 7-like 2 (TCF7L2) gene polymorphisms." (PMID 35341056, 2022). "Our study aimed to investigate the association of TCF7L2 intronic SNPs rs290487 and rs290481 with dyslipidemia in Balinese population." (PMID 35341056, 2022). "In this study, we investigated the associations of TCF7L2 SNPs, rs290487 and rs290481, with dyslipidemia and altered lipid profile in the Balinese." (PMID 35341056, 2022). "Our findings showed that the TCF7L2 rs290487 and rs290481 C alleles were significantly associated with dyslipidemia and high TC levels." (PMID 35341056, 2022). "In this study, we have shown that TCF7L2 rs290487 and rs290481 C allele were significantly associated with dyslipidemia, high LDL-C, and high TC in Balinese population." (PMID 35341056, 2022). "Further studies are warranted to explore rs290487 and rs290481 influence on the other lipid fractions (VLDL, chylomicron, ApoE, etc.), to understand on how TCF7L2 gene polymorphisms influence on dyslipidemia." (PMID 35341056, 2022). "In summary, TCF7L2 rs7903146 has a great impact on metabolic balance, linking dyslipidemia and hyperglycemia, and results in greater risk of CVD in T-allele carriers, especially in T2D patients." (PMID 34568447, 2021). "Various studies have demonstrated an association of TCF7L2 variants with features of metabolic syndrome, including elevated systolic and diastolic blood pressure, increased triglyceride levels, and elevated uric acid." (PMID 27907035, 2016). "We hypothesize that TCF7L2 SNPs rs290487 and rs290481 might also be associated with dyslipidemia in Balinese population and could be used to predict the risk of dyslipidemia." (PMID 35341056, 2022). "Moreover, it was shown that the risk of metabolic syndrome associated with TCF7L2 rs7903146 is augmented by dietary saturated fatty acid intake, with a further impairment of insulin sensitivity, which indicates that further analyses are required." (PMID 34200102, 2021). "Among the common studied allele, rs12255372 variant of the TCF7L2 gene is significantly associated with susceptibility to T2DM in the global population while the other allele (rs7903146) is associated with metabolic syndrome of which dyslipidemia is a predictor." (PMID 26608632, 2015). "In addition, several studies have suggested association between TCF7L2 rs7903146 polymorphism and dyslipidemia, but the results have been conflicting." (PMID 26576435, 2015). "Additionally, TCF7L2 is associated with MetS, dyslipidemia, and obesity markers." (PMID 40170676, 2025). "Recent studies have identified that several genetic loci traditionally associated with T2D, such as TCF7L2, IGF2BP2, and FTO, may also influence IR in individuals with T1D, particularly in those with a long disease course or features of metabolic syndrome." (PMID 41019343, 2025). "Previously, we have shown that olanzapine challenge associates an increased expression of Tcf7l2 in non-pancreatic tissues and concomitant dyslipidemia, highlighting an active interaction between olanzapine and Tcf7l2." (PMID 35874808, 2022). "Notably, individuals with at-risk alleles of Tcf7l2 displayed abnormal concentrations of TC, LCL, HDL, or very low-density lipoprotein (VDLL) in periphery blood, indicating a strong association of Tcf7l2 and dyslipidemia." (PMID 35874808, 2022). "Findings from studies on participants at risk of T2DM and participants with metabolic syndrome and T2DM reported that TCF7L2 variants did not modulate the effect of dietary interventions on glycemic parameters." (PMID 36155628, 2022).
Hyperglycemia (24 papers, 2006 to 2025). An increased concentration of glucose in the blood. "A meta-analysis study done by Chang and his colleagues reported a direct relationship between TCF7L2 alleles and the presence of chronic pregnancy hyperglycemia." (PMID 34724590, 2021). "Given this identified association between Tcf7l2 haplo-insufficiency and hyperglycaemia, we set out to investigate the potential role of canonical Wnt signalling, of which Tcf7l2 is a downstream effector, in endocrine pancreas development and/or function." (PMID 28851992, 2017). "Also, a short TCF7L2 mRNA variant in subcutaneous fat is associated with hyperglycemia and impaired insulin action in adipose tissue." (PMID 25379510, 2014). "They suggested that TCF7L2 may affect fasting and postprandial hyperglycemia in carriers of T2D risk SNPs of TCF7L2." (PMID 22934027, 2012). "To ascertain whether chronic depletion of TCF7L2 in the liver might play a causal role in the promotion of hyperglycemia, we obtained knockout mice for TCF7L2 gene in C57BL/6 background from Sanger Institute." (PMID 23028378, 2012). "Beta-cell dysfunction has been identified as the main cause by which TCF7L2 variants may exert their effects on glucose metabolism, and rs7903146 may impair the ability of hyperglycemia to suppress glucagon." (PMID 22916254, 2012). "It therefore can be further speculated that hyperglycaemia, which in turn predisposes to a proinflammatory and proatherogenic state is essential for the adverse impact of TCF7L2 on atherogenesis." (PMID 21423583, 2011). "Conversely, overexpression of a nuclear isoform of TCF7L2 in high-fat diet-fed mice ameliorated hyperglycemia with improved glucose tolerance, suggesting a role of this factor in hepatic glucose metabolism." (PMID 23028378, 2012). "As well, systemic overexpression of TCF7L2 rather promoted hyperglycemia in their BAC transgenic models." (PMID 23028378, 2012). "The mechanism by which pop-1 mediates this effect remains unclear, with further work warranted to elucidate the precise role of the TCF7L2/pop-1 homolog in rescuing hyperglycemia-induced toxicity by PARP-1 inhibition." (PMID 29392078, 2018). "For hyperglycemia, the effect of modest variants in FOXO3 might be concealed by other major variants (e. g., PEPCK, PPARG and TCF7L2) in most studies based on middle-aged subjects." (PMID 25993007, 2015). "To determine whether the effect of TCF7L2 rs7903146 on focal arteriolar narrowing was due to hyperglycemia, we further adjusted for fasting glucose values in the models, but no attenuation of genetic effects were noted." (PMID 20478041, 2010). "If these findings can be replicated in a clinical setting, the TCF7L2 rs7903146T allele may help clinicians identify nondiabetic inpatients at greater risk for accelerated glucose intolerance and hyperglycemia in an inpatient setting." (PMID 35477971, 2022). "Overall, the zebrafish Tcf7l2 mutant, characterized by hyperglycemia, pancreatic and vascular defects, and reduced regeneration proves to be a suitable model to study the mechanism of action and the pleiotropic effects of Tcf7l2, the most relevant T2D GWAS hit in human populations." (PMID 28851992, 2017). "The TCF7L2 rs7903146T genotype did not predict development of clinically diagnosable hyperglycemia (fasting blood glucose ≥ 126 mg/dl) or impaired glucose tolerance (2-h OGTT blood glucose ≥ 140 mg/dl) following bed rest." (PMID 35477971, 2022). "Decreased TCF7L2 protein levels in T2DM correlated with the downregulation of GIP and GLP-1 receptors (GIP-R and GLP-1R), and impaired β-cell function, lead to fasting and postprandial hyperglycaemia." (PMID 32090124, 2020). "Given that the effect of GIP on insulin secretion is diminished or absent during hyperglycemia, but our TCF7L2 x GIPR interaction seems to impact insulin secretion during the whole hyperglycemic clamp, a role of an acute GIP effect is not probable." (PMID 30846969, 2019).
Hyperglycemia (continued). "In the case of GDM, expression of TCF7L2 was decreased in visceral adipose tissue from women who developed hyperglycemia, although after adjusting for BMI, the difference was not significant." (PMID 25973943, 2015). "Polymorphisms in the TCF7L2 and near the CDKNZA/B genes may be of great importance for CAD development because these genes modulate both conditions and are not necessarily related to hyperinsulinaemia or hyperglycaemia." (PMID 23331854, 2013).
gastric cancer (21 papers, 2020 to 2026). A primary or metastatic malignant neoplasm involving the stomach. "Previous research has shown that frameshift mutations in Wnt pathway regulators like AXIN2 and TCF7L2 are common in gastric cancers with high MSI, further linking Wnt pathway dysregulation to tumor progression." (PMID 40444048, 2025). "Frameshift mutations in TCF7L2 gene had been found in colorectal and gastric carcinomas with high MSI." (PMID 32466784, 2020). "In terms of overcoming drug resistance, the interaction of phosphoglycerate dehydrogenase (PHGDH) with IGF2BP1 can facilitate the m6A-dependent stabilization of transcription factor 7 Like 2 (TCF7L2) mRNA to confer multidrug resistance in gastric cancer." (PMID 40986143, 2025). "TCF7L2 enhances Anoikis resistance and metastasis of gastric cancer through transcriptional activation of PLAUR25." (PMID 39730379, 2024). "In gastric cancer, the expression of TCF7L2 was upregulated, promoting the progression of gastric cancer by forming a positive feedback loop with Wnt7B." (PMID 39060928, 2024). "TCF7L2 enhances anoikis resistance in gastric cancer, whereas cell migration‐inducing protein promotes anoikis resistance in prostate tumors by activating the miR‐1248/TM9SF4 axis." (PMID 38785271, 2024). "A recent investigation found that TCF7L2 exhibits high expression levels in gastric cancer (GC) and is an independent risk factor for bad prognosis in GC patients, with evidence suggesting that it contributes to both anoikis resistance and the metastatic cascade." (PMID 37965453, 2023). "Among the corresponding tumours in the TCGA database, the overexpression of the oncogene TCF7L2 was only found in gastric cancer." (PMID 37393582, 2023). "TCF7L2 can promote gastric cancer metastasis by regulating PLAUR and forming a MIR100HG/hnRNPA2B1/TCF7L2 axis to promote CRC metastasis." (PMID 38818308, 2024).
Glucose intolerance (20 papers, 2011 to 2025). Glucose intolerance (GI) can be defined as dysglycemia that comprises both prediabetes and diabetes. "Paradoxically, some evidence indicates that liver and other tissues appear to be involved in TCF7L2 rs7903146T-associated glucose intolerance and insulin secretion." (PMID 35477971, 2022). "Loss of Tcf7l2 selectively from the β cell in mice has previously been shown to cause glucose intolerance and to lower β cell mass." (PMID 29967064, 2018). "At the heart of the contradiction is the direction of change in TCF7L2 expression leading to glucose intolerance and T2D susceptibility." (PMID 25398947, 2015). "Glucose intolerance that was associated with global haploinsufficiency of TCF7L2 was almost completely abolished by hepatic expression of TCF7L2." (PMID 23028378, 2012). "HFD-fed liver-specific Tcf7l2 knockdown mice were found to suffer glucose intolerance and gluconeogenic upregulation compared with the control group, indicating an essential role of Tcf7l2 in maintaining glucose homeostasis." (PMID 40149867, 2025). "Adipocyte expression of TCF7L2 gene in visceral adipose tissue was significantly higher in those with glucose intolerance as compared to NGT." (PMID 36263318, 2022). "We also found a significant positive correlation between expression of TCF7L2 gene in visceral adipose tissue and PPTg parameters such as TgAUC and PeakTg levels in subjects who had varying levels of glucose intolerance." (PMID 36263318, 2022). "Clearly, more research is required to understand the precise role of TCF7L2 and its adipose tissue expression in adipogenesis and adipocyte function in relation to glucose intolerance and T2DM." (PMID 36263318, 2022). "Our study illustrates that olanzapine induces weight gain, fasting insulin elevation, glucose intolerance, and increase of TCF7L2 protein expression in liver, skeletal muscle, and adipose tissues of mice." (PMID 29713286, 2018). "Other studies support the conclusion that Tcf7l2 overexpression in the periphery leads to glucose intolerance." (PMID 25398947, 2015). "A link between increased expression of Tcf7l2 and glucose intolerance phenotypes has been further supported by mouse models." (PMID 25398947, 2015). "Next, we determined if the reduced Tcf7l2 expression in beta cells and the subsequent worsening of glucose intolerance are coupled with changes in plasma insulin content." (PMID 25398947, 2015). "Here, we use a humanized mouse model overexpressing Tcf7l2, resulting in glucose intolerance, to infer the contribution of Tcf7l2 overexpression in beta cells and in other tissues to the metabolic phenotypes displayed by these mice." (PMID 25398947, 2015). "Recent work from Guy Rutter's laboratory has shown that a beta cell-specific knock-out of Tcf7l2 leads to decreased beta cell volume, decreased insulin secretion, and subsequent glucose intolerance in mice fed high fat diet." (PMID 25398947, 2015). "Pancreas-specific Tcf7l2 −/− (pTcf7l2) mice showed age-dependent glucose intolerance by 20 weeks of age when challenged with an intraperitoneal glucose bolus." (PMID 23710470, 2013). "Transgenic mice with Tcf7l2 overexpression driven by the human BAC sequence exhibited glucose intolerance when placed on a high fat diet." (PMID 23710470, 2013). "Acute depletion of TCF7L2 in the liver promoted glucose intolerance and up-regulation of gluconeogenic genes, while ectopic expression of TCF7L2 in DIO mice improved glucose tolerance." (PMID 23028378, 2012). "Hepatic Tcf7l2 depletion exacerbated HFD-induced glucose intolerance and insulin intolerance without causing changes in body weight." (PMID 36759348, 2023). "The increased adipose tissue expression of TCF7L2 gene in our study in subjects with glucose intolerance may reflect the known phenotypic differences in adipose tissue morphology and distribution in both these populations." (PMID 36263318, 2022).